IFNG (interferon gamma)
Diseases named in the same sentence as IFNG in open-access papers (continued):
Sharing a sentence is not in itself a finding about the gene and the disease.
influenza (continued). "Interestingly, both the exposure of PBMCs to 500 nm and 3 μm influenza conjugates resulted in a significant increase in the frequency of CD4+ T cells producing IFNγ and TNFα and in total amounts of these cytokines compared to exposure of PBMCs to unconjugated particles." (PMID 35890185, 2022). "However, this discrepancy could be explained by the relatively low induction of IFNγ by influenza in our system, or by differences in the kinetics of IFNγ protein and its downstream transcripts." (PMID 35428875, 2022). "In mice challenged with influenza who had normal upper airway microbiota, macrophages activated genes associated with anti-viral activity such as interferon-gamma, while mice treated with antibiotics failed to activate these pathways and had more severe lung disease." (PMID 36246273, 2022). "In one study we showed that increasing IFNγ:IL-10 ratios at pre-and 4-weeks post-vaccination were associated with protection against A/H3N2-LCII during the 2003–2004 influenza season when there was an A/H3N2 vaccine strain mismatch and influenza began to circulate in late November." (PMID 33430191, 2021). "In addition to IFNγ signaling (877300) and apoptosis (109581), it also revealed changes in epithelial-initiated B cell receptor signaling (983705 and 1168372) and amino acid metabolism (71291) following influenza infection." (PMID 31461941, 2019). "Neutralization of IFNγ (M1) and/or Arginase 1 (M2) impaired bacterial clearance in Stat2−/− mice during super-infection, demonstrating that pulmonary macrophages expressing a mixed M1/M2 phenotype promote bacterial control during influenza-bacterial super-infection." (PMID 30337919, 2018). "Since our previous studies demonstrated Treg induction and suppression of adaptive T cell responses (decreased CD8+ IFNγ+ (Tc1) and CD4+ IFNγ+ (Th1) cells numbers) after exposure to EPFRs, we studied whether depletion of Tregs would restore the adaptive T cell response towards influenza." (PMID 28086957, 2017). "Thus expression of IL-2 in the anti-influenza response may be regulated mainly by short term variability, whereas different T cell subsets, Th1 and Thpp, may contribute to variability in IFNγ expression." (PMID 24788814, 2014). "Importantly, peptides enriched for non-cross-reactive A/California/04/09 specificities induced a higher proportion of Thpp-like IFNγ−IL-2+TNFα+ CD4 T cells than peptide pools cross-reactive with previous influenza strains, which induced more Th1 (IFNγ+TNFα+) responses." (PMID 23526940, 2013). "At such early stages of infection no virus-specific lymphocytes were present in lungs to produce IFNγ, the obligate IDO inducer in lung stromal cells, suggesting that innate immune cells such as macrophages and NK T cells may release IFNγ in response to initial influenza infection." (PMID 23785507, 2013). "The allele HLA-DRB1*04:01 has been observed to confer greater resistance to influenza (H1N1) by eliciting robust immune responses through more effective T cell activation and increased interferon-gamma (IFN-γ) production." (PMID 41425584, 2025). "Furthermore, using a mouse model of severe influenza disease, we demonstrate that high IL-18Rα expression on effector T cells is associated with exacerbated disease outcomes and identify CD8 T cells with enhanced IFNγ production, but reduced cytotoxic effector molecules." (PMID 41285788, 2025). "IL‐6 KO mice have a similar inflammatory cytokine profile to WT mice during post‐influenza MRSA pneumonia, including GM‐CSF, RANTES, TNFα, IFNγ, and IL‐4." (PMID 39921246, 2025). "The number of influenza-specific CD4+ polypositive T cells, defined as CD4+ T cells producing at least two of the following immune markers: CD40L, IFNγ, IL-2, and TNFα, exhibited similar trends between cohorts at any visit for any vaccine strain." (PMID 39340066, 2024).
influenza (continued). "ORFVΔ121conH1-immunized/CA/09-challenged pigs had a significant higher frequency of IFNγ+ CTLs in PBMCs and TBLN-MNC, indicating the induction of influenza-specific CD8+T cells." (PMID 37112974, 2023). "Upon influenza infection, the established CD8+ TRM cells show a predominant skewing towards the original type-1 response, with the cells mainly able to produce IFNγ." (PMID 37696824, 2023). "All but six of these proteins (CCL11, CXCL11, IFNγ, MCP-2, SCF, and TRAIL) were significantly less expressed in patients with influenza." (PMID 35264246, 2022). "It has previously been demonstrated that iNKT cells activate ILC1s to secrete IFNγ and stimulate ILC2s to produce IL5 during influenza infection in the lung." (PMID 33513946, 2021). "A demonstration of the lowering effect of IFNγ in the lung, induced by ADPN, comes from a study in which the number of IFNγ-producing influenza-specific T cells was diminished." (PMID 34445677, 2021). "In the case of influenza reactive CD8 T cells, both Granzyme B (p = 0.0002) and IFNγ (p = 0.0059) producing CD8 T cells dominated the pre-existing CD8 T cell responses at baseline." (PMID 33922875, 2021). "Serum concentration of IL-6, IL-1β, TNFα, IFNγ were found elevated in cases of HAdV, RSV, and influenza AURTIs compared to age-specific normal values." (PMID 33066100, 2020). "The role of IFNγ, and its production in recall lung CD8 T cell responses is established in controlling influenza viral lung replication." (PMID 33767689, 2020). "Adults have been shown to have a broad and diverse influenza-specific CD4 T cell repertoire, with cytokine production enriched for IFNγ and typically considered to be “Th1-biased”22." (PMID 30692574, 2019). "During influenza infection NK cell-derived IFNγ is also required for optimal cytotoxic T lymphocyte (CTL) function and recall responses are augmented by NK cell IFNγ production." (PMID 29552008, 2018). "For detection of CD4+ and CD8+ T cells responding to any influenza protein, splenocytes from sequentially infected or sequentially immunized mice were stimulated overnight with WIV, and IFNγ production was assessed by intracellular cytokine staining." (PMID 30356772, 2018). "The up-regulation of IL-8, IFNγ and CCL3 has been related to lung recruitment of neutrophils, NK and T cells and the development of severe influenza infection." (PMID 27825367, 2016). "Formulations with AS03B (especially the 0.003 μg/dose) also generated more influenza-specific CD4+ and CD8+ T cells than the unadjuvanted or AS03A-adjuvanted vaccines, although these cells were primarily single positive for IFNγ." (PMID 25972874, 2015). "Both groups showed a diminished IFNγ response to PPD, CMV, Influenza and LPS when compared to HIV-TB+ controls (p≤0.027) and to LPS and influenza when compared to HIV-TB- controls (p≤0.015)." (PMID 25415590, 2014). "More influenza NP- and PA-specific BAL CD8+ T cells were present, and higher proportions of these cells expressed intracellular IFNγ and IL-10 in PR8-infected IDO1-KO mice." (PMID 23785507, 2013). "BAL cells and PBMCs from carriage negative volunteers were stimulated with pneumococcal antigens (HK-6B or 6B c/s) or influenza and cytokine (TNF, IL-17A or IFNγ) producing CD4+ memory T-cells were subsequently detected by ICS and flow cytometry." (PMID 23555269, 2013). "Both in influenza- and in PVM-infected mice, BAL NK cells displayed an activated phenotype (high CD69) and produced IFNγ upon stimulation ex vivo, indicating that they were functional." (PMID 22940382, 2012). "Overall, our results support the notion of IL-6, IFNγ and perhaps MCP-1 as potential indicators for more severe influenza disease." (PMID 22808082, 2012). "IFNγ, KC, and TNF-α all were under expressed in the lungs of influenza infected E2 mice compared to placebo controls." (PMID 22792357, 2012).
influenza (continued). "Patients infected with highly pathogenic H5N1 have been shown to have higher levels of systemic IFNγ, IL-6, interferon-inducible protein of 10 kD (IP-10) and MCP-1 compared to individuals infected with human influenza subtypes." (PMID 21731666, 2011). "During singular influenza infection, increased IFNγ, albeit not at statistically significant levels, was observed at Day 7 post‐influenza infection." (PMID 40420617, 2025). "Similarly, in live infection models, we and others have identified IFNγ signalling a key player in AM training after BCG vaccination, influenza infection, pneumococcal infection, and intranasal infection with an adenoviral vector." (PMID 40624927, 2025). "Similarly, seasonal influenza vaccination generated CIML NK cells in a cohort of 52 previously unvaccinated individuals, with these cells displaying enhanced IFNγ responses to cytokine stimulation for months post-vaccination." (PMID 39599860, 2024). "Efforts into producing a more effective influenza vaccine have found that an intranasal nanoparticle vaccination elicited a persistent, polyfunctional CD4+ T cell response producing IFNγ and TNFα in murine models, which mediates survival from a lethal challenge with H1N1 influenza virus." (PMID 38317404, 2024). "Moreover, the frequency of IL-17A+ and IFNγ+CD8+ T lymphocytes in TBLN-MNC were significantly higher at DPC6 than those of sham-immunized/CA/09-challenged pigs, suggesting induction of influenza-specific CD8+ T cells." (PMID 37112974, 2023). "We observed an increase in proliferation of CD4 T cells in human blood cells after both influenza viral challenge and IFNγ stimulation, as marked by the upregulation of Ki-67, but no increase in proliferation was detected after stimulation of NHP blood cells." (PMID 36624212, 2023). "In addition, after stimulating CD4+CXCR5+Tfh cells with an influenza antigen, it was found that the level of CD40 L in the OS group was significantly reduced and the level of IFNγ was increased considerably." (PMID 35494526, 2022). "Upon influenza infection of the recipients, GFP+ ILC2s were found to have downregulated GATA3 expression and upregulated IL-12Rβ2 and IL-18Rα, becoming so-called ex-ILC2s that produced IFNγ upon ex vivo stimulation with IL-12 and IL-18." (PMID 36052086, 2022). "GO term “Viral Gene Expression”, as well as pathways related to influenza infection were upregulated in CM4; while response to virus, response to interferon gamma and innate immune response, pathway of the adaptive immune response and interferon signaling were significantly down-regulated in CM4." (PMID 33718452, 2021). "As reviewed by Van Reeth et Ma in 2013, an intranasal route or an endotracheal route using a lower swIAV dose lead to slower and lower viral load peaks in lungs, milder lung inflammation (lower levels of IFNa, IFNg and pro-inflammatory cytokines in BALF) and less influenza-specific symptoms." (PMID 33917103, 2021). "IL-10 has also been found to be 3-fold higher, and the ratio of IFNγ:IL-10 significantly lower, in elderly subjects that developed influenza compared to those that did not." (PMID 36845567, 2021). "Next, we evaluated the cytokine polarization of the cellular responses of Flucelvax, and consistent with what was found in pre-existing influenza-specific responses at baseline, vaccine-specific CD4 T cells produced primarily IFNγ cytokines and exhibited a dominant Th1 polarized profile." (PMID 33922875, 2021).
influenza (continued). "We isolated CD4+ T cells from the spleens of influenza or ECTV infected mice, co-cultured with BMDCs presenting MHCII peptides derived from either direct presentation or indirect presentation and measured T cell activation using an IFNγ ELISpot." (PMID 32745153, 2020). "Similar to other innate lymphocytes, γδ T cells exert anti-influenza activity either by direct killing or noncytolytic inhibition of virus replication through the secretion of IFNγ." (PMID 31612153, 2019). "After 12 months, 56 (31 girls/25 boys) of the 70 children had been re-infected or infected with a new strain of influenza A/H1N1, A/H3N2, and/or B, as indicated by at least a four-fold increase in the HI antibody titer and/or a two-fold increase in IFNγ-positive SFU." (PMID 30866564, 2019). "In all experiments, mice that were immunized with WIV alone developed no or very few IFNγ ELIspot secreting cells (7–55 spots/spleen million cells), which was not significantly higher than influenza naïve control mice." (PMID 31315253, 2019). "Secretion of IFNγ downstream of iNKT cell activation was previously shown to enhance the cytolytic activities of NK as well as virus-specific CD8+ T cells, resulting in reduced influenza viral burden and enhanced survival." (PMID 31440243, 2019). "We identified differences in both the specificity and functionality of influenza-specific CD4 T cells between these subject cohorts, with children having less elaboration of IFNγ upon antigenic stimulation and decreased immunodominance of the internal virion proteins when compared to adults." (PMID 30692574, 2019). "However, influenza-specific CTL activity and IFNγ production by memory T cells in response to influenza challenge decline with aging and are poorly stimulated by inactivated influenza vaccines." (PMID 26941738, 2016). "In a pre-clinical model using human PBMC to test different adjuvants combined with split-virus influenza vaccines (SVV), we have shown that addition of toll-like receptor (TLR) agonists can be used to improve the IFNγ:IL-10 ratios as well as GrB responses to influenza challenge." (PMID 27322555, 2016). "In birds and mammals, influenza-specific CD8+ cytotoxic cells become activated and produce IFNγ during infection in response to the engagement of their T cell receptors with influenza-derived peptides in the context of MHCI on the surface of antigen presenting cells (APC)." (PMID 25450002, 2015). "In contrast, the influenza infection in non-vaccinated control mice predominantly drove the induction of IFNγ-producing CD4+ T cells." (PMID 24465206, 2014). "Unlike CMV and LPS, however, we did not observe significantly increased or decreased IFNγ responses to any of the TB-antigens, nor to Influenza in TB-IRIS patients." (PMID 25415590, 2014). "We analyzed IFNγ ELISpot responses to CMV, influenza, TB and LPS before ART and during TB-IRIS." (PMID 25415590, 2014). "In contrast, the tetanus- and influenza-specific 2+γ- populations only developed high levels of IFNγ expression if cultured in Th1-inducing conditions, not in Th2 conditions." (PMID 24788814, 2014). "The human CD4 T cell memory response to influenza is normally skewed strongly to the Th1 pattern of cytokine expression, including mainly cells secreting IFNγ, TNFα and IL-2 but not IL-4." (PMID 23526940, 2013). "In contrast, no influenza-driven IFNγ-producing cells were detected in PBMC from pigs vaccinated with the non-adjuvanted whole vaccine or mock-vaccine at any time-point (adjusted P = 0.99, n = 3)." (PMID 22427834, 2012). "We found that influenza-specific IFNγ production by CD4 and perhaps CD8 T cells or the absence of the KLRG1+CD57+ influenza-specific tetramer positive population each independently predict influenza antibody responses upon vaccination." (PMID 21887299, 2011).
influenza (continued). "It is currently not known what role TNFα plays in controlling influenza infection but, like IFNγ, TNFα is known to have direct antiviral effects and is a dominant cytokine produced during influenza virus infections." (PMID 20544035, 2010). "On IL-4 stimulation, we saw an upregulation of Ki-67 in human CD4 T cells but not NHP cells, much akin to IFNγ stimulation, and high expression of pSTAT3 in the natural killer of IL-4-stimulated blood cells, but not in PBMCs from humans challenged with influenza." (PMID 36624212, 2023). "Of note, the LAIV-immunized hamsters also demonstrated increased IFNγ production after challenge with SARS-CoV-2, most probably due to the nonspecific activation of SARS-CoV-2-specific T cells by the presence of robust T-cell immunity to influenza after LAIV immunization." (PMID 35891306, 2022). "Moreover, both the 500 nm and 3 μm influenza conjugates induced significantly higher numbers of cytokine-producing CD4+ T cells and induced increased production of the pro-inflammatory cytokines IFNγ and TNFα." (PMID 35890185, 2022). "However, despite the lower frequencies of influenza-specific T-cells found in CMV-seropositive older individuals, they exhibited a significantly higher IFNγ T-cell response to influenza virus in the acute phase of the disease compared to CMV-seronegative older individuals." (PMID 34576140, 2021). "While Il6 and Ifnγ expression were increased with influenza infection, regardless of vaccination status and viral burden, transcripts of Il6 were not significantly changed in NK cell depleted mice, while Ifnγ showed a trend for a decrease in NK cell depleted mice." (PMID 32117282, 2020). "Finally, SAA3−/− mice demonstrate increased mortality in response to H1N1 influenza infection, along with higher copy number of viral RNAs in the lung, a lack of CD8+ T cell IFNγ secretion, and decreased flu-specific antibodies." (PMID 30410021, 2018). "Influenza infected women without ILI symptoms had a higher magnitude of IFNγ producing CD8+ T cells, compared to those reporting symptoms, as measured in ELISpot assays after stimulation with the pdm09 virus or peptides representing conserved CD8+ T cell epitopes (uCD8i)." (PMID 29145441, 2017). "However, IFNγ is not crucial for the host response to influenza infection whereas, interferons type I and III are essential." (PMID 26921172, 2016). "In addition, the scrambled negative control peptide as well as influenza-derived peptide did not induce detectable levels of IFNγ (and data not shown), which ruled out the non-specific effects at the concentrations used (20 μM)." (PMID 24363024, 2014). "Thus in human influenza-specific memory CD4 T cells, the IFNγ+ cells may variably express IL-2, but 2+γ- cells may include cells with a distinct differentiation state." (PMID 24788814, 2014). "The enhanced induction of both IFNγ and TNF by Fluzone adjuvanted with GLA-SE could positively impact an influenza vaccination program aimed at the elderly population since prior studies have reported a putative correlation of cell mediated immunity and protection against influenza." (PMID 21060869, 2010). "The immunopathogenic effects of NK cell accumulation and IFNγ release within delicate lung tissues are well known in both influenza and RSV infection and may go some way to explaining the increased survival and lowered morbidity seen in NK cell depleted mice infected with influenza." (PMID 29552008, 2018). "However, the lack of difference in IL-4 and IFNγ production could be attributed to the lack of strong CD4+ or CD8+ T cells epitopes in influenza HA protein in C57BL/6 mice that is restricted by H-2b47." (PMID 27404789, 2016). "Indeed, no influenza-driven IFNγ was detected in the supernatants of PBMC from pigs vaccinated with the adjuvanted split vaccine isolated at any other day following the vaccination, or at any time-point from pigs vaccinated with either the non-adjuvanted whole vaccine or mock-vaccine (P>0.1, n = 3)." (PMID 22427834, 2012).